ENSG00000285713 (novel transcript)
Gene: Protein-coding gene on chromosome 4 (144,210,701 to 145,098,174, reverse strand). Ensembl gene ENSG00000285713.
Genetic constraint (gnomAD): Missense variants: 32 observed, 45.36 expected, observed/expected ratio (o/e) 0.71, 90% interval 0.53 to 0.95. Synonymous variants: 19 observed, 16.36 expected, observed/expected ratio (o/e) 1.16, 90% interval 0.81 to 1.68.